EML4 (EMAP like 4)
Diseases named in the same sentence as EML4 in open-access papers (continued):
Sharing a sentence is not in itself a finding about the gene and the disease.
lung cancer (continued). "First, we tested the growth inhibitory properties of crizotinib on a series of lung cancer cells lines including SPC-A1, HCC827, H1975 and A549, and found that although none of these cell lines harbors an EML4-ALK fusion protein, most of them were responsive to crizotinib treatment." (PMID 26384345, 2015). "Although the EML4-ALK fusion gene is a minor genetic abnormality in NSCLC, the incidence of lung cancer is increasing in many countries, the absolute number of lung cancer patients harboring the EML4-ALK fusion gene is not trivial." (PMID 23741400, 2013). "In addition to TFG-ALK in lung cancer, some ALK fusions have been reported without histopathological evidence: TPM4-ALK in esophageal squamous cell carcinoma and EML4-ALK in colon and breast carcinomas." (PMID 22347464, 2012). "Since EML4-ALK V3, but not V1, is sequestered to microtubules in the presence of ALK-TKIs, we tested whether the addition of vincristine could enhance the cytotoxicity of ALK-TKI (crizotinib or ceritinib) in ALK-positive lung cancer cell lines." (PMID 35159046, 2022).
non-small cell lung carcinoma (198 papers, 2009 to 2026). A group of at least three distinct histological types of lung cancer, including non-small cell squamous cell carcinoma, adenocarcinoma, and large cell carcinoma. "For example, the EML4 (echinoderm microtubule-associated protein-like 4)-ALK (anaplastic lymphoma kinase) fusion gene has been linked to non-small cell lung cancer, while BCR-ABL has been associated with chronic myeloid leukemia." (PMID 40584293, 2025). "In a previous matched tissue-blood analysis, 21% of ALK-positive non-small cell lung cancer patients showed multiple tumor-specific EML4::ALK variants, indicating the existence of fusion-defined tumor heterogeneity evident at the genomic level." (PMID 40041857, 2025). "The oncogenic potential of ALK is predominantly driven by genetic alterations, including fusion rearrangements, most notably the EML4-ALK fusion in non-small cell lung cancer, activating point mutations, and gene amplification." (PMID 41614760, 2025). "A recent case report has identified EML4-ALK variant 3a/b as a mechanism of acquired resistance to osimertinib in a patient with EGFR L858R-positive non-small cell lung cancer." (PMID 41357203, 2025). "It was not until 2007 that the first instance of the echinoderm microtubule-associated protein-like 4 (EML-4)–ALK rearrangement in non-small-cell lung cancer (NSCLC) was documented." (PMID 39001519, 2024). "In a specific group of non-small-cell lung carcinoma patients, a genetic abnormality involving echinoderm microtubule–associated protein-like 4 (EML4) has been discovered." (PMID 38894711, 2024). "The EML4 (echinoderm microtubule-associated protein-like 4)-ALK (anaplastic lymphoma kinase) fusion gene in non-small-cell lung cancer (NSCLC) was first identified in 2007." (PMID 36982897, 2023). "Fusion of ALK with echinoderm microtubule-associated protein-like 4 (EML4) has been reported in approximately 5% of non-small cell lung cancer (NSCLC)." (PMID 38264745, 2023). "Numerous fusion partners of ALK have been identified (e.g., nucleophosmin (NPM)-ALK in anaplastic large cell lymphoma (ALCL) and echinoderm microtubule-associated protein-like 4 (EML4)-ALK in non-small cell lung cancer (NSCLC))." (PMID 37954850, 2023). "The EML4(e21)::ALK(e20) fusion with non-canonical breakpoint of EML4 gene at exon 21 has been reported to constitute only about 2% of the ALK-rearrangements in non-small cell lung cancer, where EML4(e6)::ALK(e20) is the most common EML4::ALK variant." (PMID 35237889, 2022). "Crizotinib, the first clinically approved drug to target ALK, is a tyrosine kinase inhibitor that was approved for use in echinoderm microtubule-associated protein-like 4 EML4-ALK-positive non-small-cell lung cancer (NSCLC)." (PMID 35508387, 2022). "EML4-ALK oncoprotein is associated with 6.7% of the non-small-cell lung cancer and 2% of medullary thyroid cancer." (PMID 35008858, 2021). "Chromosomal inversions involving anaplastic lymphoma kinase (ALK) and echinoderm microtubule associated protein like 4 (EML4) generate a fusion protein EML4-ALK in non-small cell lung cancer (NSCLC)." (PMID 33761896, 2021). "Echinoderm microtubule-associated protein-like 4 (EML4) is the canonical anaplastic lymphoma kinase (ALK) fusion partner in non-small cell lung cancer (NSCLC), and ALK-positive patients showed promising responses to ALK tyrosine kinase inhibitors (TKIs)." (PMID 33363027, 2020). "Next-generation sequencing was used to detect the mutation of EML4-ALK in 1505 non-small cell lung cancer patients, including 1208 tissue samples and 297 blood samples." (PMID 32047559, 2020). "The mutation of EML4-ALK in the tissue samples of 399 patients with non-small cell lung cancer was detected by reverse transcription polymerase chain reaction." (PMID 32047559, 2020). "EML4-ALK is commonly associated with non-small cell lung cancer; NPM1-ALK is most frequent in anaplastic large cell lymphoma." (PMID 30675517, 2019).
non-small cell lung carcinoma (continued). "The discovery of EGFR mutations and EML4-ALK gene rearrangements has radically changed the therapeutic scenario for patients with advanced non-small cell lung cancer." (PMID 28938691, 2017). "Echinoderm microtubule-associated protein-like 4- anaplastic lymphoma kinase EML4-ALK gene rearrangements are present in around 5% of non-small cell lung carcinoma (NSCLC) patients." (PMID 28805673, 2017). "Subsequently, in 2007, ALK was found fused to echinoderm microtubule associated protein-like 4 (EML4) yielding the fusion kinase EML4-ALK seen in approximately 3–5% of non-small cell lung cancers (NSCLC)." (PMID 27009859, 2016). "The echinoderm microtubule-associated protein-like 4—ALK (EML4-ALK) fusion was identified in 2% -7% of non-small cell lung cancer (NSCLC) patients." (PMID 25742289, 2015). "The echinoderm microtubule-associated protein like 4 (EML4)-ALK in non-small cell lung cancer (NSCLC) was first discovered as an oncogenic driver gene in 2007; the EML4-ALK fusion gene was generated by an inversion in the short arm of chromosome 2." (PMID 26253541, 2015). "Patients with non-small cell lung cancer (NSCLC) with echinoderm microtubule-associated protein-like 4 (EML4)-anaplastic lymphoma kinase (ALK) rearrangements generally respond to ALK inhibitors such as crizotinib." (PMID 25096400, 2014). "The echinoderm microtubule-associated protein-like 4 anaplastic lymphoma kinase (EML4-ALK) fusion gene has been identified as a potent oncogenic driver in non-small-cell lung cancer, in particular adenocarcinoma." (PMID 25527865, 2014). "The translocations of the anaplastic lymphoma kinase (ALK) gene with the echinoderm microtubule-associated protein-like 4 (EML4) gene on chromosome 2p have been identified in non-small-cell lung cancers (NSCLCs) as oncogenic driver mutations." (PMID 25407901, 2014). "Recently, a novel gene fusion involving ALK and echinoderm microtubule-associated protein-like 4 (EML4) was discovered in non-small cell lung carcinoma (NSCLC)." (PMID 24156086, 2013). "A fusion gene that joins the echinoderm microtubule-associated protein-like 4 (EML4) gene with the anaplastic lymphoma kinase (ALK) gene was found in a subset of non-small-cell lung carcinomas (NSCLCs) in 2007." (PMID 23922677, 2013). "The first cancer diagnostic product-ExoDX Lung (ALK) was launched by Exosome Diagnostics in 2016, which is an exosome-based technology detecting RNA and ctDNA simultaneously and performing real-time screening for EML4-ALK mutations in patients with non-small cell lung cancer (NSCLC)." (PMID 41220804, 2025). "In 2016, the world’s first cancer diagnostic product based on exosome miRNAs body fluid biopsy, ExoDx Lung (ALK), was launched, which could detect EML4-ALK mutations in patients with non-small cell lung cancer in real time." (PMID 36678650, 2022). "Anaplastic lymphoma kinase (ALK) rearrangement has also been reported in non-small cell lung carcinomas, such as Echinoderm microtubule-associated protein-like 4-anaplastic lymphoma kinase (EML4-ALK) fusion identified in a lung adenocarcinoma metastasis to the thyroid." (PMID 35328664, 2022). "The clinical phenotype of non-small cell lung cancer (NSCLC) with the fusion gene echinoderm microtubule associated protein like 4 (EML4) - anaplastic lymphoma kinase (ALK), is characterised by early metastasis and poor prognosis in comparison to tumours without a known oncogenic driver." (PMID 32762670, 2020). "Besides, selective anaplastic lymphoma kinase (ALK) inhibitors is a first-line therapy for nucleophosmin (NPM)-ALK-positive T cell lymphoma and echinoderm microtubule-associated protein like 4 (EML4)-ALK-positive non-small cell lung cancer (NSCLC)." (PMID 32493414, 2020). "Furthermore, other ALK fusion proteins shall be discussed, such as echinoderm microtubule-associated protein-like 4 (EML4)-ALK which is implicated in non-small cell lung carcinoma (NSCLC)." (PMID 31366041, 2019).
non-small cell lung carcinoma (continued). "Furthermore, two secondary mutations in the kinase domain of the fusion protein EML4-ALK were discovered in non-small-cell lung cancer in tumor cells isolated from a patient during the relapse phase of treatment with the ALK inhibitor PF-02341066." (PMID 22192458, 2011). "Characterization of aberrant oncogenic signaling in non-small-cell lung cancer (NSCLC) has resulted in precision cancer medicine treatment approaches via tyrosine kinase inhibitors (TKIs) towards mutated epidermal growth-factor receptor (EGFR) or EML4-ALK fusions." (PMID 33671772, 2021). "The fusion between anaplastic lymphoma kinase (ALK) and echinoderm microtubule-associated protein-like 4 (EML4) is a causative factor in a unique subset of patients with non-small cell lung carcinoma (NSCLC)." (PMID 26517679, 2015). "Inhibitors targeting EML4-ALK fusion proteins have emerged as crucial therapeutics for ALK-positive non-small cell lung cancer." (PMID 40584293, 2025). "Examples include the BCR::ABL1 gene fusion in patients with CML and ALK fusions (e.g. EML4::ALK) in non-small-cell lung cancer." (PMID 41421967, 2025). "Non-small cell lung cancer (NSCLC) cells with EML4-ALK fusions (H228) showed sensitivity (IC50=118.4 nM)." (PMID 39900433, 2025). "Supporting evidence of PETI, the EML4-ALK fusion gene which is a feature of many non-small cell lung cancers was simulated in HEK293T cells by applying pegRNAs targeting intronic regions of EML4 and ALK with RTTs homologous to the other locus." (PMID 39609594, 2025). "Crizotinib 1 is an approved first generation ALK inhibitor (IC50 vs. EML4-ALK = 250–300 nM) used to treat ALK-positive non-small cell lung cancer (NSCLC)." (PMID 38338677, 2024). "F-circEA1 in non-small-cell lung cancer (NSCLC) also results from the fusion of the EML4 and ALK1 genes." (PMID 38892280, 2024). "For instance, the BCR-ABL fusion transcript is a defining marker for chronic myeloid leukemia (CML), while EML4-ALK fusions are found in a subset of non-small-cell lung cancers." (PMID 39857631, 2024). "The EML4–ALK oncogene drives tumour progression in approximately 5% of cases of non-small-cell lung cancers." (PMID 39682703, 2024). "Several malignancies, especially non-small cell lung cancer, have a unique genetic change known as the EML4-ALK E13:A20 gene rearrangement." (PMID 38306516, 2024). "The resulting EML4-ALK fusion gene product represents a novel molecular target for the treatment of non-small cell lung cancer." (PMID 38953007, 2024). "Although EML4–ALK fusions are observed in only 4%–5% of yearly diagnosed non-small cell lung cancer cases, the remarkable response to ALK inhibitor drugs has led to universal testing for all patients with advanced non-small cell lung cancer." (PMID 38894711, 2024). "In fact, numerous, alternate fusion partners have been documented following the discovery of ALK translocations, for example EML4-ALK-positive non-small-cell lung cancer (NSCLC) and other solid tumours." (PMID 37414143, 2023). "ALK is also frequently rearranged (EML4–ALK) in some solid tumors particularly non-small-cell lung carcinoma (NSCLC)." (PMID 36909156, 2023). "CircRNA F-circEA, originating from the EML4-ALK fusion gene, is enriched in the plasma of EML4-ALK-positive non-small cell lung cancer (NSCLC), serving as an additional “liquid biopsy” biomarker for NSCLC." (PMID 38933287, 2023). "Specifically, the circular RNA F-circEA derived from the EML4-ALK fusion gene has emerged as a novel liquid biopsy biomarker for non-small cell lung cancer." (PMID 38098508, 2023). "EML4-ALK fusions are reported in 5% of non-small cell lung carcinoma, but are rare in atypical carcinoids with only five previously reported cases." (PMID 35350512, 2022). "A fusion between EML4 (echinoderm microtubule-associated protein-like 4) and ALK was identified in non-small-cell lung cancer (NSCLC) in 20073." (PMID 35999456, 2022).
non-small cell lung carcinoma (continued). "ALK fusion is an important driver mutation that accounts for approximately 3-7% of non-small cell lung cancer (NSCLC) cases, and the most common form is EML4-ALK." (PMID 36275795, 2022). "Anaplastic lymphoma kinase (ALK) fusion, an important oncogenic mutation, occurs in 3% to 7% of non-small cell lung cancer (NSCLC) cases, and EML4 is the most common partner gene." (PMID 35446297, 2022). "Other evidence is present in the literature that supports this, e.g., the comparison of RT-PCR with an NGS pipeline for the detection of EML4-ALK fusions in non-small cell lung cancer FFPE samples." (PMID 36338518, 2022). "As another example, in 2007, EML4–ALK was identified as a novel fusion oncogenic driver of non-small cell lung cancer (NSCLC)." (PMID 33557176, 2021). "Examples of fusion genes discovered with the help of modern genomics include: the TMPRSS2-ERG in prostate cancer, RET-CCDC6 in thyroid carcinoma, and EML4-ALK in non-small cell lung cancer (NSCLC)." (PMID 33946483, 2021). "Rearrangements of the anaplastic lymphoma kinase (ALK) gene have been identified in approximately 3–7% of non-small cell lung cancer (NSCLC) patients, with echinoderm microtubule-associated protein like-4 (EML4) representing the most common fusion partner." (PMID 34271921, 2021). "ALK inhibitors effectively target EML4-ALK positive non-small cell lung cancer, but their effects are hampered by treatment resistance." (PMID 33907223, 2021). "Most of these EML4-ALK-positive non-small cell lung cancer patients respond well to the ALK inhibitor." (PMID 34034462, 2021). "One compelling example is the development of crizotinib in patients with non-small cell lung cancer (NSCLC) with ALK rearrangement into an EML4-ALK fusion protein." (PMID 34199382, 2021). "The echinoderm microtubule-associated protein-like 4 (EML4)-anaplastic lymphoma kinase (ALK) fusion oncogene, arising from an inversion on chromosome 2, was discovered in 2007 and is found in 5% of non-small cell lung cancers (NSCLC) worldwide." (PMID 32300555, 2020). "This is represented by the discovery of EML4-ALK fusion in ~ 4% of non-small cell lung cancer and FGFR-TACC fusion in ~ 3% of glioblastomas that have culminated in effective targeted therapies in these tumors." (PMID 32771039, 2020). "EML4-ALK fusions are targetable oncogenic drivers in a subset of advanced non-small cell lung cancer (NSCLC) patients that can benefit from selected ALK inhibitors." (PMID 32850382, 2020). "About 3–5% of non small cell lung cancer (NSCLC) harbor Anaplastic lymphoma kinase (ALK)-rearrangement, mainly with echinoderm microtubule-associated protein-like 4 (EML4) as a gene partner." (PMID 31906956, 2020). "In this case study, a non-small cell lung cancer patient harboring EML4-ALK demonstrated an initial response to treatment with Crizotinib, but subsequently demonstrated resistance following the acquisition of the ALK C1156Y mutation (top left)." (PMID 30675517, 2019). "Perhaps the most widely recognized is the echinoderm microtubule-associated protein-like 4 (EML4)-ALK fusion, identified in 5–6% of non-small-cell lung cancer (NSCLC) patients in 2007." (PMID 29495603, 2018). "Molecular testing revealed the EML4-ALK fusion protein in approximately 5% of patients with non-small cell lung cancer." (PMID 29732013, 2018). "Of these 6 cases, 5 were non-small cell lung cancer expressing EML4-ALK and one case was myofibroblastoma expressing PPFIBP1-ALK." (PMID 29535836, 2018). "One common mechanism of ALK activation in tumors is ALK gene rearrangement leading to fusion protein like NPM-ALK in anaplastic large cell lymphomas and EML4–ALK in non-small-cell lung cancer." (PMID 28359267, 2017). "Identification of targetable EML4-ALK fusion proteins has revolutionized the treatment of a minor subgroup of non-small cell lung cancer (NSCLC) patients." (PMID 27495736, 2016).